SPHK2 (sphingosine kinase 2)
Diseases named in the same sentence as SPHK2 in open-access papers (continued):
Sharing a sentence is not in itself a finding about the gene and the disease.
tumor (continued). "Lathyrol and cisplatin inhibit the proliferation of RCC xenografts, reduce the protein expression levels of AR, CYP17A1, SPHK2, PARP1, E-cadherin, and ZO-1 in tumor tissues (P < 0.05), and promote the protein expression levels of N-cadherin, β-catenin, vimentin and α-SMA (P < 0.05)." (PMID 38965120, 2024). "TRIM22 induces SPHK2/MAPK signaling activation in GBM, driving tumor growth and progression." (PMID 37258577, 2023). "Since no information is available regarding immunohistochemical localization of SphK2, SGPP1, and LPP3 in OSCC, thus, in the present study, we have analyzed the expression of SphK1, SphK2, SGPP1, and LPP3 in tumor tissues from OSCC patients and benign oral mucosa by immunohistochemistry (IHC)." (PMID 35494957, 2022). "Expression of SphK2 in adjacent non-malignant epithelium showed moderate to strong cytoplasmic positivity, whereas low expression was noted in tumor cells." (PMID 35494957, 2022). "In multivariate linear regression analysis, tumor size was an independent negative predictor of SphK2 expression." (PMID 35494957, 2022). "In the present work, this minor hepatic FC increase was not sufficient to overwhelm the tumor-suppressive effects of Sphk2-KO." (PMID 36333295, 2022). "Pharmacological inhibition (with ABC294640) of sphingosine kinase 2 (SphK2), one of the two Sphk isoforms that catalyzes the synthesis of S1P from sphingosine, effectively reduced CRPC cell proliferation and xenograft tumor growth by targeting AR and the oncogene MYC." (PMID 34386430, 2021). "We found that knockdown of either SphK1 or SphK2 effectively reduced IFITM1 and KAL1 expression indicating sphingolipid metabolism indeed regulates these cellular genes expression and functions to determine tumor cell survival." (PMID 32626514, 2020). "The SPHK1 sphingosine Kinase 1 isozyme has been largely studied and its several functions in tumor development have been demonstrated, while the SPHK2 has not been as well-studied." (PMID 32211323, 2020). "Particularly, previous observations have revealed an additive effect of the selective sphingosine kinase 2 (SPHK2) inhibitor ABC294640 together with sorafenib on cell toxicity and death in HCC cells in vitro and the increased suppression of tumor growth in murine HCC models." (PMID 32244391, 2020). "The SPHK1 isozyme has been extensively characterized and its diverse functions in tumor progression documented, while SPHK2 has not been as well characterized and its primary physiological functions are controversial." (PMID 31891125, 2018). "In vivo, SphK2 silence, by targeted-shRNA or miR-19a-3p, inhibited U2OS tumor growth in nude mice." (PMID 29285269, 2017). "We recently reported that targeting SphK2 using either RNA interference or a selective small-molecule inhibitor, ABC294640, induces caspase-mediated apoptosis for KSHV-infected PEL cells and suppresses PEL tumor progression in vivo." (PMID 26327294, 2015). "We have previously demonstrated that targeting SphK2 using a novel selective inhibitor, ABC294640, leads to intracellular accumulation of ceramides and induces apoptosis for KSHV-infected PEL cells, while suppressing tumor progression in vivo." (PMID 26327294, 2015). "There have been reports indicating that selective blockers of SphK2 induce autophagy in tumor cells of kidney, prostate, breast, and T-cell acute lymphoblastic leukemia, ultimately resulting in nonapoptotic cell death and delayed tumor development." (PMID 37852968, 2023). "Altogether, both endogenous SPHK1-derived S1P and SPHK2-derived S1P have shown to function independent of their S1P receptor signaling by binding to specific intracellular targets, thereby regulating genes involved in tumor growth/progression." (PMID 35565311, 2022).
tumor (continued). "Tumor size (standardized coefficient β = −0.562, p = 0.035), gender (standardized coefficient β = −0.444, p = 0.040), and smoking status (standardized coefficient β = −2.240, p < 0.001) were found to be an independent negative predictor of SphK2 expression." (PMID 35494957, 2022). "In cancer cells, S1P produced by SPHK2 acts as an inhibitor of the class I histone deacetylases HDAC1 and HDAC2 to enhance gene transcription, particularly genes activated by hypoxia, and couples to the catalytic subunit of telomerase to enable tumor cell replication and avoid senescence." (PMID 35163211, 2022). "Inhibiting SPHK2 decreases the growth of tumor cells, and expression of wild-type hTERT, but not the S1P-binding hTERT mutant, potentiates cancerous growth, which indicates that, under some circumstances, Sphk2 functions as a proto-oncogene." (PMID 34055895, 2021). "As different tumour cells are differentially equipped with Sphk1 and Sphk2, those cells with high levels of Sphk1 have low Sphk2 levels, and vice versa, it may well be possible that in certain tumour or non-tumour cell types, hypoxia could also affect Sphk2 expression." (PMID 36984866, 2023). "On the other hand, SPHK2, another isoform of SPHK, did not exhibit any positive correlation in terms of tumor subtypes, grade, stage, disease progression, and overall survival rate." (PMID 39284838, 2024). "Since compound A does not inhibit murine SPHK2, the human MDA-MB-231 xenograft model was utilized to study the effect of complete SPHK inhibition on tumor growth in vivo." (PMID 23861887, 2013).
infection (17 papers, 2014 to 2026). The state of being infected such as from the introduction of a foreign agent such as serum, vaccine, antigenic substance or organism. "Furthermore, SphK2-deficient neutrophils expressed lower levels of the immunosuppressive marker CD244 during infection." (PMID 41660628, 2026). "While SphK2 has been associated with regulation of the replication process of viruses including influenza A virus, little is known regarding its function in host immunity to infection." (PMID 34696381, 2021). "SPHK2 expression was modestly regulated upon Ctr infection in M2Φ, with a twofold upregulation 24 h p.i.." (PMID 40249190, 2025). "The time course of the cytokine release in SphK2−/− mice was similar to wt mice with highest levels 6 h post infection." (PMID 36361636, 2022). "We found that there was still a large amount of SPHK2 accumulation maintaining in the nucleus at 24 h post-infection with IAV." (PMID 36070294, 2022). "To search for potential other explanations for the improved survival rate of SphK1/2 deficient mice, we analyzed the cytokine profile in plasma of wt, SphK1−/− and SphK2−/− mice before and at 6 h, 24 h and 14 d post infection." (PMID 36361636, 2022). "Subsequent determination of S1P levels in plasma 6 h, 24 h and 14 d post infection revealed an early drop of 40% (Δ 416 nM) in wt mice, 45% (Δ 163 nM) in SphK1−/− mice and 15% (Δ 362 nM) in SphK2−/− mice." (PMID 36361636, 2022). "The levels of SphK2 and phosphorylated SphK2 were significantly increased in A549 cells upon infection with IAV H1N1 as well as IAV H3N2 and influenza B virus." (PMID 31783527, 2019). "This study sheds light on the key role played by SPHK2 in facilitating the PA infection in the host and how the ‘hijacking’ of the host genome by the invading organism can be resisted by blocking the SPHK2/S1P pathway." (PMID 31842752, 2019). "Future work will be needed to fully determine SphK2′s role in promoting CHIKV replication by co-localizing with the CHIKV replication complex during infection." (PMID 31783527, 2019). "In these structures, SphK2 localized with CHIKV dsRNA during early infection stages, leading the authors to suggest a potential role for SphK2 in regulating viral gene expression." (PMID 31783527, 2019). "In this manuscript we have delved into the genomics of Sphk2−/− as the mechanism of PA infection stimulating phosphorylation of SPHK2 mediated by protein kinase C (PKC) δ and its localization in epithelial cell nucleus has already been described by us." (PMID 31842752, 2019). "In this context, we noted that genes in the PKC pathway have undergone significant differential regulation following infection with PA of both WT and Sphk2−/−groups." (PMID 31842752, 2019). "Two-way analysis of variance (ANOVA) analysis was performed and differentially expressed genes following PA infection were identified using whole transcriptome of Sphk2−/− mice and their WT counterparts." (PMID 31842752, 2019). "Recently, sphingosine kinase 2 (SK2) was identified as a selective CHIKV host factor that co-localized with CHIKV replication complex during infection." (PMID 29751486, 2018). "The results showed that the pattern of increased SphK2 phosphorylation upon infection with meningitic E. coli was similar between HBMEC expressing dominant-negative EGFR and HBMEC expressing the control vector." (PMID 27711202, 2016). "Moreover, virus titers in SPHK2 overexpressed A549 cells were increased by approximately 1.2-log (P<0.0001) at 24 h post infection, while the viral titers in SPHK2 knockout A549 cells dropped more than 1.3-log (P<0.01), compared to that in the WT A549 cells." (PMID 36070294, 2022). "SphK2−/− mice had overall diminished levels of all investigated pro-inflammatory cytokines that did not significantly alter compared to naïve control levels except for TNF-α at 6 h post infection." (PMID 36361636, 2022).
infection (continued). "Interestingly, it has been reported that SPHK2 functions differently during the infection of different genotypes of HCV." (PMID 36070294, 2022). "Often, effects on the immune system dominate the overall antiviral response, as for example, in the case of persistent lymphocytic choriomeningitis virus (LCMV) infection of mice, where inhibition of the SphK2 stimulates the T cell response and elimination of the infection." (PMID 34658908, 2021). "The effects on viral resolution could even be observed if the inhibitor was given after the establishment of a chronic viral infection, which suggests that SphK2 is important for sustaining T cell exhaustion during the chronic stage of infection." (PMID 34696381, 2021). "In addition, we also noted that genetic deletion of Sphk2 resisted alteration of host pulmonary genome by PA infection by promoting its own virulence." (PMID 31842752, 2019). "This indicates that PA-induced activation of Furin is somehow dependent on SphK2 gene activity and could be the principal mechanism through which host combats PA infection." (PMID 31842752, 2019). "Nevertheless, our results are in general agreement with a single study reporting cytomegalovirus (CMV) regulation of lipid biosynthesis pathways wherein CMV infection increased SphK activity, SphK1 and SphK2 mRNA expression, and SphK1 protein expression following de novo infection." (PMID 25010828, 2014). "Therefore, we sought to establish whether targeting SphK2 induces apoptosis selectively for KSHV-infected primary human endothelial cells following de novo infection, and if so, to identify putative mechanisms for SphK2-mediated survival of these cells." (PMID 25010828, 2014). "Cells transfected with control vector pCMV-Myc (-), SPHK2-WT or SPHK2-G212E expressing plasmids were infected with WSN virus and cells were collected for Western blotting analysis at 24 h post infection." (PMID 36070294, 2022). "Not only did the RNAseq experiment confirm our RT-qPCR results (i.e., upregulation of SPHK1 and SPHK2 but also SGPL1 and SGPP1), but also revealed regulation of additional SL metabolism genes upon infection, in addition to a vast array of inflammatory mediators." (PMID 40249190, 2025). "Accordingly, the bacterial load in blood and liver was not different between wt, SphK1−/− and SphK2−/− mice 6 h and 24 h post infection." (PMID 36361636, 2022). "Interferon-γ (IFN-γ) was only detectable at very low levels in plasma 6 h post infection and not different in wt, SphK1−/− and SphK2−/− mice." (PMID 36361636, 2022). "However, after 6 h of infection with IAV, SPHK2 were distributed not only in the cytoplasm, but also in the nucleus, and displayed an obvious accumulation in the nucleus." (PMID 36070294, 2022). "Infection of mouse lung with P. aeruginosa increased NOX4 expression in WT and Sphk1−/− mice; however, there was no robust increase in the expression of NOX4 in the lungs of Sphk2−/− mice exposed to P. aeruginosa." (PMID 33802941, 2021). "The gene expression levels of S1P synthases (Sphk1, Sphk2) and S1P hydrolases (Sgpl1) in the liver, e-WAT, lung, heart, and aorta of mice were measured by real-time PCR under the infection conditions where a significant increase in plasma S1P concentration was observed." (PMID 34635791, 2021). "Interestingly, PA infection of WT mouse lung inhibited HDAC1/2 activity, and enhanced H3 and H4 histone acetylation, however, genetic deletion of Sphk2 in mice attenuated PA mediated H3 and H4 histone acetylation." (PMID 31842752, 2019). "Finally, S1P from nuclear-localized SPHK2 can bind and inhibit the function of histone deacetylase (HDAC), which influences infection and apoptosis in other viruses." (PMID 29145490, 2017).
inflammation (4 papers, 2015 to 2023). Aberrant reaction of the microcirculation characterized by movement of fluid and leukocytes from the blood into extravascular tissues. "Chronic peripheral inflammation (CPI) caused a bilateral increase in mechanical sensitivity in Sphk2−/− mice." (PMID 26283908, 2015). "However, administration of S1P1 agonist in SphK2−/− mice markedly suppressed CFTR expression, abolished the protective effect of SphK2 deficiency on small airways remodeling and pulmonary inflammation after CS exposure." (PMID 36226596, 2023). "Likewise, inhibiting SPHK2 or deleting SphK2 in a mouse model of renal inflammation and fibrosis decreases inflammation and fibrotic responses, resulting in lessened renal injury." (PMID 34055895, 2021). "Thus, our results suggest that, in contrast to PSC/UC patients, the upregulation of the SPHK2/S1P axis may be responsible for chronic intestinal inflammation and could promote the transformation to dysplastic changes in UC patients." (PMID 37298127, 2023).
neurodegenerative disease (1 paper, 2021). A disorder of the central nervous system characterized by gradual and progressive loss of neural tissue and neurologic function. "Overall, the SPHK2/S1P pathway is under investigation in several age-associated neurodegenerative diseases, but it is still necessary to learn if changes in the pathway in these disorders are a cause or an effect of neuronal malfunction." (PMID 34055895, 2021). "SPHK2 is clearly involved in neurodegenerative diseases, but whether and how SPHK2 regulates the initiation and progression of AD, PD, HD, and other neurodegenerative diseases has not yet been thoroughly investigated." (PMID 34055895, 2021).
neurological disease (1 paper, 2024). "Notably, many of these DEGs have been associated previously with neurological disease including SPHK2 (sphingosine kinase 2); P2RX7 (purinergic receptor P2X 7); SMPD4 (sphingomyelin phosphodiesterase 4); ASAH1 (N-acylsphingosine amidohydrolase 1)." (PMID 38625017, 2024).
SPHK2 also shares sentences with these, for which no sentence is quoted: adenocarcinoma (2 papers); biliary atresia (2); diffuse large B-cell lymphoma (2); ischemic stroke (2); lupus nephritis (2); T-cell acute lymphoblastic leukemia (2); acute kidney injury (1); adenoma (1); alcoholic cirrhosis (1); alcoholic liver diseases (1); amyloid (1); amyotrophic lateral sclerosis (1); asthma (1); astrocytoma (1); autism (1); Brain atrophy (1); cardiac hypertrophy (1); chondrosarcoma (1); chronic obstructive pulmonary disease (1); dementia (1); dermatitis (1); diabetic cardiomyopathy (1); diabetic nephropathy (1); disc degeneration (1); endothelial dysfunction (1); Erythema (1); hemolytic-uremic syndrome (1); hippocampal atrophy (1); hypertriglyceridemia (1); hypopharyngeal squamous cell carcinoma (1).
A further 15 diseases each share a sentence with SPHK2 in 1 paper.